LINC01285 (long independently transcribed non-coding RNA 1285)
Gene: Long non-coding RNA gene on chromosome X (118,839,538 to 118,919,669, forward strand). Ensembl gene ENSG00000203650.
Gene Ontology:
Biological process: miRNA-mediated post-transcriptional gene silencing